TAF11L6 (TATA-box binding protein associated factor 11 like 6)
Tractability: No criterion of Open Targets' tractability assessment is met for any kind of drug.
Gene: Protein-coding gene on chromosome 5 (17,528,669 to 17,529,265, forward strand). Ensembl gene ENSG00000284042.
Gene Ontology:
Molecular function: RNA polymerase II general transcription initiation factor activity; protein heterodimerization activity
Biological process: RNA polymerase II preinitiation complex assembly; transcription initiation at RNA polymerase II promoter
Cellular component: transcription factor TFIID complex; nucleus
Homologues: Orthologues: tropical clawed frog taf11 (45% identical), zebrafish taf11 (45% identical), Drosophila melanogaster Taf11 (42% identical), Caenorhabditis elegans taf-11.1 (33% identical), Caenorhabditis elegans taf-11.2 (27% identical). Paralogues in human: TAF11L10 (100% identical), TAF11L5 (100% identical), TAF11L7 (100% identical), TAF11L8 (100% identical), TAF11L3 (99% identical), TAF11L4 (99% identical), TAF11L9 (99% identical), TAF11L13 (95% identical), TAF11L2 (92% identical), LINC02218 (88% identical), TAF11L12 (87% identical), TAF11L11 (85% identical), and 2 more.